TRAJ4 (T cell receptor alpha joining 4)
Gene: T-cell receptor joining (J) gene on chromosome 14 (22,542,199 to 22,542,261, forward strand). Ensembl gene ENSG00000211885.
Diseases named in the same sentence as TRAJ4 in open-access papers:
TRAJ4 is named in the same sentence as 1 disease in open-access papers, as found by Europe PMC text mining. Sharing a sentence is not in itself a finding about the gene and the disease.
TRAJ4 shares sentences with these, for which no sentence is quoted: anaplastic large cell lymphoma (1 paper).